MBOAT7 (membrane bound acylglycerophosphatidylinositol O-acyltransferase MBOAT7)
Diseases named in the same sentence as MBOAT7 in open-access papers (continued):
Sharing a sentence is not in itself a finding about the gene and the disease.
liver disease (continued). "Collectively, these studies identify MBOAT7-driven acylation of LPI lipids as an important modulator of both liver disease progression and associated type 2 diabetes." (PMID 31621579, 2019). "The steatogenic alleles in PNPLA3, TM6SF2, GCKR and MBOAT7 all associated with increased risk of ICD‐defined ‘other diseases of liver’ (K76), which includes NAFLD (n = 408 455, P = 0.0075–2 × 10−12)." (PMID 29280273, 2018). "In the present study, we investigated the role of rs641738 C > T genetic variant in MBOAT7 in Moroccan patients with a broad spectrum of liver disease." (PMID 30116012, 2018). "Furthermore, the PI remodelling enzyme membrane-bound O-acyltransferase 7 (MBOAT7) has been recently associated with severe liver disease, with loss of function promoting hepatic steatosis, inflammation and fibrosis." (PMID 41032702, 2025). "MBOAT7 is a transmembrane protein involved in phosphatidylinositol remodeling, and its rs641738C>T variant, strongly contributes to pathogenesis of a range of liver diseases in human genetic studies." (PMID 35579278, 2022). "Collectively, over the past 6 years, numerous human studies have linked genetic variation in the MBOAT7 locus to various diseases, prompting several groups to follow up using animal models to establish causal links to liver disease progression and other related phenotypes." (PMID 35636492, 2022). "first reported that genetic deletion of Tmc4 in mice may not lead to hepatic steatosis, but the loss of function of its neighboring gene Mboat7 could result in liver disease progression in mice." (PMID 34113561, 2021). "The hypothesis that MBOAT7 is the causal gene underlying the association with liver disease at the locus is supported by the observation that mice deficient for MBOAT7 have altered hepatic concentrations of polyunsaturated phosphatidylinositol." (PMID 32882372, 2021). "Our findings are in line with results previously reported in other ethnicities describing the association between the MBOAT7 variant and chronic liver disease and suggest that the rs641738 is the causal genetic variant influencing expression level of MBOAT7 and increasing the risk to liver disease." (PMID 32443539, 2020). "Based on eQTL studies in the liver it has been suggested that instead reduced expression and activity of MBOAT7 may be mechanistically linked to liver disease progression." (PMID 31621579, 2019). "Moreover, the major substrate of MBOAT7, lysophosphatidylinositol, has been proposed to be a crucial mediator for progression of obesity-linked liver disease, as MBOAT7 knockdown in mice treated with lysophosphatidylinositol lipids worsened hepatic inflammatory and fibrotic gene expression." (PMID 38247511, 2024). "In addition, this approach helped in characterizing the genetic basis shared by NAFLD with other liver diseases as well as with other metabolic disorders, by identifying a role for variants in membrane bound O-acyltransferase domain-containing 7 (MBOAT7), IFNL3/IFNL4 and FNDC5 in NAFLD." (PMID 32824337, 2020). "Therefore, we cannot rule out that alterations in PIP-dependent signal transduction may also play a role in MBOAT7 loss of function-driven liver disease progression." (PMID 31621579, 2019). "Therefore, the MBOAT7 variation might have a dual impact on liver disease during initial stages: either predisposes to HCC development before severe fibrosis ensues, or it facilitates the evolution to early-intermediate fibrosis." (PMID 28674415, 2017). "We observed that patients who were minor homozygous for genetic variants previously related to predisposition to liver disease (PNPLA3 and MBOAT7) had increased phase I enzyme activity." (PMID 37686209, 2023). "Following up on these ASO and MPO knockdown studies in 2021, three independent laboratories generated hepatocyte-specific Mboat7 knockout mouse lines to better understand the cell autonomous role for MBOAT7 in liver disease progression." (PMID 35636492, 2022).
liver disease (continued). "A hot genetic variant, rs641738 within the membrane-bound O-acyltransferase domain containing 7(MBOAT7) and transmembrane channel-like 4 (TMC4), was recently reported to be associated with several liver diseases." (PMID 34113561, 2021). "The rs641738 (T) allele remained independently associated with low hepatic MBOAT7 mRNA expression after adjustment for age, sex, BMI, alanine aminotransferase (ALT) and severity of liver disease (estimate −0.095±0.02; P=0.03)." (PMID 27630043, 2016). "Herein, we review recent insights into the mechanisms by which MBOAT7-driven phosphatidylinositol remodeling influences liver disease progression and discuss how rapid progress in this area could inform drug discovery moving forward." (PMID 35636492, 2022). "To more directly test the hypothesis that LPI lipids may promote liver disease in a Mboat7-dependent manner, we directly treated mice with LPI lipids to transiently increase circulating LPI levels within a physiologic level (~2 fold)." (PMID 31621579, 2019). "These disturbances suggest that the rs641738 T allele may modulate the inflammation process independently of the etiology of the liver disease by down-regulating the MBOAT7 expression and protein synthesis." (PMID 30116012, 2018). "Recently it has been suggested that LPIAT1 is a major contributor to liver disease, with a loss-of-function variant near MBOAT7 gene associated with various liver diseases such as metabolic-associated fatty liver disease, nonalcoholic fatty liver disease, and alcohol-associated liver disease." (PMID 37250116, 2023). "Therefore, genetic variants in PNPLA3/TM6SF2/MBOAT7/HSD17B13 do not impact the regression of portal hypertension and clinical outcomes in patients with pre-treatment ACLD after CHC cure." (PMID 33917196, 2021). "Given the fact that Mboat7 knockdown is associated with increases in LPI lipids, we next hypothesized that MBOAT7 substrate LPI lipids themselves may be the main drivers of liver disease progression under conditions of HFD-induced obesity and Mboat7 loss of function." (PMID 31621579, 2019). "Despite the wealth of data about the putative role of MBOAT7 variation in the progression of liver diseases, no data assessing the relationship between the MBOAT7 rs641738 genetic variant and earlier steps of the disease ie. spontaneous clearance of HBV and HCV infection is available so far." (PMID 30116012, 2018). "Nowadays, the functional mechanisms of MBOAT7 action in liver diseases remain unknown." (PMID 30116012, 2018). "To address this, we have studied ethanol-induced liver injury in mice selectively lacking Mboat7 in hepatocytes or myeloid cells, given the key roles that hepatocytes and myeloid cells play in the pathogenesis of ethanol-induced liver disease progression." (PMID 38648183, 2024). "None of the polymorphisms of TM6SF2, MBOAT7, GCKR, nor the PRS, were associated with increased risk of development of severe liver disease in the full cohort." (PMID 36166317, 2022). "In conclusion, genetic variants in PNPLA3, TM6SF2, MBOAT7, and HSD17B13 do not seem to impact the short-term regression of portal hypertension." (PMID 33917196, 2021). "To determine if MBOAT7 expression is an adaptive response consequent to liver injury, we compared MBOAT7 expression in CHC with low fibrosis (F0–F1) (n=45) with 28 controls without liver disease." (PMID 27630043, 2016). "Furthermore, we show that Mboat7, but not Tmc4, loss of function in mice is sufficient to drive NAFLD progression, and show that Mboat7 substrate lipids (LPIs) may be critical mediators of obesity-linked liver disease progression." (PMID 31621579, 2019).
Cirrhosis (21 papers, 2017 to 2026). A chronic disorder of the liver in which liver tissue becomes scarred and is partially replaced by regenerative nodules and fibrotic tissue resulting in loss of liver function. "The PNPLA3 I148M variant was also associated with HCC development outside cirrhosis, with a similar effect size of that of MBOAT7 variation (p = 0.021)." (PMID 28674415, 2017). "Given previous studies have shown that MBOAT7 is a risk locus for alcohol-associated cirrhosis, we investigated whether active alcohol consumption was associated with alterations in MBOAT7 function." (PMID 38648183, 2024). "Over 50% of cirrhosis patients had at least one risk variant in PNPLA3, MBOAT7 and GCKR, while 13.0% had at least one risk variant in TM6SF2." (PMID 36854015, 2023). "We examined the association of all-cause cirrhosis with six genetic variants previously reported to be associated with alcoholic or non-alcoholic cirrhosis: PNPLA3 I48M, TM6SF2 E167K, MBOAT7 rs641738, HSD17B13 rs72613567, HFE C282Y and SERPINA1 E366K." (PMID 32282858, 2020). "Notably, this correlation exists independently of PNPLA3, TM6SF2, and MBOAT7, with a stronger association for NAFLD/ALD cirrhosis than other risk factors." (PMID 40004054, 2025). "MBOAT7 catalyzes the transfer of fatty acids between phospholipids and lysophospholipids, and the SNP rs641738 is associated with higher risk of NAFLD and inflammation and fibrosis in chronic hepatitis B, while rs626283 is correlated with ALD cirrhosis." (PMID 31340446, 2019). "In detail, variants rs738409 in PNPLA3, rs641738 in MBOAT7, and rs58542926 in TM6SF2 are associated with increased triglyceride production, accumulation of very low-density lipoprotein (VLDL) and triglycerides and increased risk of developing cirrhosis, respectively." (PMID 36835291, 2023). "In future studies, it will be important to examine how Mboat7 loss of function impacts the development of fibrosis in appropriate fibrosis-prone animal models, and whether Mboat7 expression in hepatic stellate cells plays a regulatory role in the progression from NASH to cirrhosis." (PMID 31621579, 2019). "No statistical significance was observed for the OR of SNPs in MBOAT7, HSD17B13, and TM6SF2 in MASLD-related cirrhotic HCC compared with cirrhosis." (PMID 40995436, 2025). "Hepatocytes with reduced MBOAT7 expression have increased proliferation and migration, which may explain the association of reduced MBOAT7 expression, such as with the rs641738 TT MBOAT7 genotype, with an increased risk of hepatocellular carcinoma in NAFLD patients without cirrhosis." (PMID 38893234, 2024). "Although some proposed mechanisms behind this have been put forth, we still do not completely understand how defective MBOAT7-driven PI remodeling can promote the progression from simple steatosis to NASH, fibrosis, cirrhosis, or even HCC." (PMID 35636492, 2022).
steatosis (21 papers, 2017 to 2025). Increased lipid within the cytoplasm of cells. "Although we have gained some mechanistic understanding of how Mboat7 loss of function can promote steatosis in mouse models, there are still many unanswered questions that remain." (PMID 35636492, 2022). "In individuals who carried GCKR rs1260326, PNPLA3 rs738409, TM6SF2 rs58542926, and MBOAT7 rs641738 variants (n = 218 NAFLD/445 total) there was a fivefold increased risk of steatosis (OR: 4.97, 95% CI 2.51–9.83)." (PMID 31969816, 2019). "For instance, several single nucleotide polymorphisms (SNPs) such as patatin-like phospholipase domain-containing protein 3 (PNPLA3), transmembrane six superfamily member 2 (TM6SF2) and membrane bound O-acyltransferase domain-containing 7 (MBOAT7) appear to be associated with steatosis progression." (PMID 35696400, 2022). "In mice, acute MBOAT7 silencing conveys hepatic fat entrapment and MBOAT7−/− hepatocytes acquire a cell-autonomous property to accumulate giant LDs, supporting the idea that MBOAT7 may be causally involved in steatosis onset." (PMID 34680476, 2021). "Variants in PNPLA3, GCKR, MBOAT7, and TM6SF2 were variably associated with liver injury and steatosis markers, with cohort-specific effects." (PMID 40943344, 2025). "Notable single nucleotide polymorphisms (SNPs), including PNPLA3 rs738409, TM6SF2 rs58542926, MBOAT7 rs641738, and GCKR rs1260326, are consistently linked to steatosis, inflammation, and fibrosis in MASLD." (PMID 40943344, 2025). "Hispanic ethnicity and genetic polymorphisms in PNPLA3, TM6SF2, GCKR, MBOAT7, and HSD17B13 are associated with steatosis-related lipotoxicity and oxidative DNA damage, which can contribute to hepatocarcinogenesis." (PMID 40995256, 2025). "In conclusion, we demonstrate that hepatocyte-specific deletion of Mboat7 in mice results in steatosis and elevated liver function tests, consistent with the human pathology." (PMID 32859645, 2021). "Hepatic removal of both SREBP cleavage-activating protein (Scap) and Mboat7 normalized hepatic triglycerides relative to Scap-only hepatic KO, showing that increased SREBP-1c processing is required for Mboat7-induced steatosis." (PMID 32859645, 2021). "Histological hematoxylin-eosin and trichrome staining of liver sections showed marked steatosis in the chow-fed Mboat7 LSKO mice." (PMID 32859645, 2021). "This demonstrates that cleavage activity of SREBPs by Scap is required for Mboat7 LSKO-induced steatosis." (PMID 32859645, 2021). "We therefore examined several potential mechanisms driving the mixed hepatic steatosis in Mboat7 ASO-treated mice." (PMID 31621579, 2019). "Indeed, PNPLA3 was associated with a higher risk for both steatosis and hepatic fibrosis, while TM6SF2 was primarily linked with steatosis and MBOAT7 with hepatic fibrosis." (PMID 38809396, 2024). "In addition, the accumulation of MBOAT7 substrate LPIs can promote steatosis and proinflammatory and profibrotic signaling under conditions where MBOAT7 function is diminished." (PMID 35636492, 2022). "To determine whether Mboat7 LSKO-induced steatosis was dependent on SREBP activation, we removed hepatic SREBP cleavage-activating protein (Scap) in Mboat7 LSKO mice." (PMID 32859645, 2021). "Expression of MBOAT7 is reduced in both obese humans and rodents fed with a high-fat diet and MBOAT7 KO mice develop steatosis, hepatic inflammation, hepatocyte cell death, and increased expression of fibrosis-associated genes due to altered levels of PI and LPI in the liver." (PMID 34069012, 2021). "Alternative models for the mechanisms for Mboat7-induced steatosis are also feasible." (PMID 32859645, 2021). "Hepatic knockdown/deletion of MBOAT7, which leads to the accumulation of its substrate LPI, exacerbates diet-induced steatosis, inflammation, cell death, fibrosis and hepatic insulin resistance in mice." (PMID 41032702, 2025).
steatosis (continued). "Mboat7 and Lpcat3 LSKO mice have similar phenotypes but differ in that Lpcat3 LSKO mice also have reduced TG-rich lipoprotein secretion rates, resulting in steatosis." (PMID 32859645, 2021). "The PNPLA3 mutation and initial steatosis grade were key predictors of MASLD improvement, while TM6SF2 (rs58542926) and MBOAT7 (rs641738) variants were not significant." (PMID 39125390, 2024). "In contrast, TM6SF2 rs58542926 and MBOAT7 rs641738 were not related to steatosis in our cohort." (PMID 35696400, 2022).
liver fibrosis (20 papers, 2017 to 2025). "Further genome-wide association studies linked transmembrane 6 superfamily 2 (TM6SF2)-rs58542926 and membrane-bound O-acyltransferase domain-containing protein 7 (MBOAT7)-rs641738 variants with liver fibrosis in patients with CHC." (PMID 33917196, 2021). "In this study we analyzed the association between TM6SF2 variant rs58542926 and MBOAT7 variant rs641738 and the risk of hepatic fibrosis or liver cirrhosis of different etiology in an Eastern European patient cohort." (PMID 30875804, 2019). "In this study, we tried to evaluate the association between TM6SF2 variant rs58542926 and MBOAT7 variant rs641738 and the risk of hepatic fibrosis or liver cirrhosis of different etiology." (PMID 30875804, 2019). "In the current study, we aimed to evaluate the associations between TM6SF2 rs58542926 and MBOAT7 rs641738 genes polymorphisms and the risk of hepatic fibrosis and liver cirrhosis." (PMID 30875804, 2019). "In addition to individual associations, we explored the potential combined effect of PNPLA3 and MBOAT7 variants on liver fibrosis using a logistic regression model that included both polymorphisms." (PMID 40650184, 2025). "This common MBOAT7 variant (rs641738, C>T), which reduces MBOAT7 expression, confers increased susceptibility to nonalcoholic fatty liver disease, alcohol-associated liver disease, and liver fibrosis in patients chronically infected with viral hepatitis." (PMID 35636492, 2022). "Additionally, we ran combined analysis to assess whether TM6SF2 and MBOAT7 SNPs mediate the risk of liver fibrosis or liver cirrhosis in the presence of certain PNPLA3 genotypes." (PMID 30875804, 2019). "Several GWASs have demonstrated that MBOAT7 rs641738 is associated with a risk of MASLD in individuals of European descent, as well as alcoholic-associated cirrhosis and liver fibrosis in chronic hepatitis C patients." (PMID 40507973, 2025). "Specifically, the common MBOAT7 variant (rs641738) associated with reduced MBOAT7 expression is implicated in non-alcoholic fatty liver disease (NAFLD), alcohol-associated liver disease (ALD), and liver fibrosis." (PMID 38648183, 2024). "The effects of PNPLA3 have been well established in previous research, but we wanted to see if the risk of liver fibrosis is changed by a certain combination of PNPLA3 and TM6SF2 or MBOAT7 genotypes." (PMID 30875804, 2019). "More recently, a GWAS conducted on patients affected by Alcoholic Liver Disease (ALD) reported an association between Membrane Bound O-Acyltransferase Domain Containing 7 (MBOAT7) polymorphisms and liver fibrosis." (PMID 28629152, 2017). "This is the first study to investigate the relationship between the PNPLA3 rs738409, TM6SF2 rs58542926, GCKR rs1260326 and rs780094, MBOAT7 rs641738, HSD17B13 rs72613567, and MTARC1 rs2642438 polymorphisms in the Brazilian population with MASLD and liver fibrosis." (PMID 40650184, 2025). "In addition, the rs641738 C > T variant, near two genes encoding membrane-bound O-acyltransferase domain-containing 7 (MBOAT7) and transmembrane channel-like 4 (TMC4), was shown to be associated with the progression of NAFLD and liver fibrosis." (PMID 34359642, 2021). "In conclusion, TM6SF2 rs58542926 as well as MBOAT7 rs641738 were not linked to hepatic fibrosis, alcohol or hepatitis C virus induced liver cirrhosis in an Eastern European population." (PMID 30875804, 2019). "Finally, the association between specific pattern of liver fibrosis and other genetic variants should be further tested, as recent evidence suggested that, TM6SF2 p.E167K, and MBOAT7 rs641738 variants are associated with increased liver steatosis and fibrosis." (PMID 29150621, 2017). "In addition, this is the first study to investigates the relationship between the rs738409 (PNPLA3), rs58542926 (TM6SF2), rs1260326 and rs780094 (GCKR), rs641738 (MBOAT7), rs72613567 (HSD17B13), and rs2642438 (MTARC1) polymorphisms in the Brazilian population with MASLD and hepatic fibrosis." (PMID 40650184, 2025).
liver fibrosis (continued). "PRS-5 based on variations in PNPLA3, TM6SF2, GCKR, MBOAT7, and HSD17B13 is also useful for the prediction of liver fibrosis." (PMID 40507973, 2025). "Here, we explore the role of a genetic variation located in membrane-bound O-acyltransferase domain-containing protein 7 (MBOAT7) gene on spontaneous clearance of HBV and HCV infections and on liver fibrosis." (PMID 30116012, 2018).